INS (insulin)
Diseases named in the same sentence as INS in open-access papers (continued):
Sharing a sentence is not in itself a finding about the gene and the disease.
diabetes (continued). "The benefits of SMBG for patients with type 1 diabetes mellitus and for insulin-treated patients with type 2 diabetes mellitus are well established, whereas those for non–insulin-treated patients have been questioned." (PMID 37606977, 2023). "Wearable insulin biosensors offer promising avenues for diabetes management but come with certain disadvantages and risks." (PMID 38239544, 2023). "Regarding diabetes, 257 patients (93.5%) used insulin pens, and 18 patients (6.5%) used the NPH-regular regimen." (PMID 38666044, 2023). "Glucose forecasting serves as a backbone for several healthcare applications, including real-time insulin dosing in people with diabetes and physical activity optimization." (PMID 36981436, 2023). "At this time, she was also on insulin and metformin for uncontrolled diabetes with an A1c level of 9% and doxazosin for persistent hypertension." (PMID 38066479, 2023). "There are a variety of antidiabetic drugs that have been developed to treat diabetes through different mechanisms, either to increase insulin levels in the body or to achieve successful islet transplantation." (PMID 36839746, 2023). "It has been well established that intensive insulin treatment compared to conventional therapy can prevent and delay diabetes complications." (PMID 36701305, 2023). "For the early diagnosis of diabetes, clinical (plasma glucose concentration, serum insulin, etc.)and physical data (for example, body mass index (BMI), age) are often used." (PMID 36832284, 2023). "This is expected as the incidence rate for type 1 diabetes, which will account for most cases of childhood diabetes requiring insulin therapy, varies markedly between countries." (PMID 36869270, 2023). "Forty-five patients had diabetes, thirty-five were taking diabetes medications, and nineteen were being treated with insulin." (PMID 36961021, 2023). "The finite regulation of insulin secretion is disrupted in diabetes, which is diagnosed when fasting glucose levels reach 7.0 mmol/L (125 mg/dL) or above." (PMID 37504117, 2023). "In the aftermath of Hurricane Katrina, one of the main concerns for people with diabetes was obtaining insulin/medication and appropriate care for their condition." (PMID 37254127, 2023). "Taken together, our results revealed an increase in the expression of trypsin-1, PAR1, 2, 3, and COX-2 in diabetes, and treatment with insulin, and especially Mg2+, markedly inhibited the expression of COX-2, trypsin protease-1, and PARs in the diabetic rats." (PMID 37228689, 2023). "The most well-known cause of hyperglycemia is diabetes mellitus, a condition that affects the body's ability to either use (type 2 diabetes mellitus - T2DM) or produce (type 1 diabetes mellitus - T1DM) insulin." (PMID 37012937, 2023). "Diabetes mellitus is a chronic metabolic condition characterized by insufficient insulin production and reduced cellular sensitivity to insulin, leading to elevated blood glucose levels and disruptions in carbohydrate, protein, and fat metabolism." (PMID 38005341, 2023). "Diabetes (DM1), has an absolute deficiency of insulin secretion and loss of insulin-producing β-cells in the pancreas by responding to a multifactorial pathogenesis linked to an autoimmune aggression mediated by autoantibodies." (PMID 37790059, 2023). "Diabetes individuals using insulin as therapeutic treatment should properly monitor glycemia levels before, during and after exercise sessions to minimize health incidents, such as hypoglycemia." (PMID 36593495, 2023). "During the extension phase, both groups will independently titrate their insulin under the remote supervision of prescribing diabetes nurse specialists following an insulin titration algorithm." (PMID 37969919, 2023). "In another study, Naïve Bayes, Decision Tree, Support Vector Machine SVM, and Random Forest were used to predict diabetes in children using glucose, blood pressure, skin thickness, insulin, BMI, age, and family history of diabetes." (PMID 36857368, 2023).
diabetes (continued). "His maternal uncle was diagnosed with diabetes at the age of 19 years and multiple other family members had a diabetes diagnosis and have been managed with insulin." (PMID 37353797, 2023). "The discovery of insulin revolutionized diabetes management and helped patients achieve better glycemic control and reduce the incidence of micro-and macrovascular complications." (PMID 36782190, 2023). "As well known, hypoglycemia in the elderly is closely related to anti-diabetes regimens like sulfonylureas and insulin." (PMID 38273819, 2023). "This study aimed to describes how adults with diabetes requiring insulin perceive diabetes apps based on 3 key psychological needs (competence, autonomy, and connectivity) described by the Self-Determination Theory (SDT) on motivation." (PMID 36826987, 2023). "Diabetes mellitus (DM) is a chronic metabolic disorder characterized by diminished insulin secretion or action resulting in hyperglycemia with subsequent complications in many organs such as the heart, retina, nervous tissue, and kidney." (PMID 37016650, 2023). "The rationale for replacing the “Diabetes Mellitus on Insulin” with HbA1C:Hemoglobin is to provide a more objective severity marker." (PMID 37035307, 2023). "At baseline, the median (range) duration of diabetes was 7.1 (4.3–11.1) years, and one‐third of participants were insulin naïve (75.2%)." (PMID 37392036, 2023). "The management of diabetes is a complex and lifelong challenge, necessitating regular monitoring of blood glucose levels and precise insulin administration." (PMID 38239544, 2023). "In terms of subjects, trials primarily included overweight and obese patients with diabetes, with 15/42 (35.7%) trials including participants using insulin." (PMID 37513574, 2023). "Nevertheless, a recent study using linagliptin (a DPP4 inhibitor) for the treatment of an adolescent patient with WS1 diabetes in addition to intensive insulin treatment, showed a dramatic decrease in exogenous insulin need with a good safety profile." (PMID 36835101, 2023). "Diabetes mellitus is another of the biggest problems in public health, characterised by defects in insulin secretion, insulin action, or both." (PMID 37050137, 2023). "Unfortunately, we found that when comparing glycemic outcomes, race remained a significant cofactor even when controlling for current age, duration of diabetes, sex, insurance status, and type of insulin administration." (PMID 40303248, 2023). "This is why plasma sIR levels in patients with type 2diabetes mellitus (T2DM) are negatively correlated with insulin sensitivity." (PMID 36818396, 2023). "Type 1 diabetes mellitus (T1DM) is a chronic autoimmune condition in which the immune system destroys insulin-making cells in the pancreas." (PMID 36979105, 2023). "Disruption of insulin signaling and abnormal activation of components of the insulin signaling pathway in the brain, features typical of diabetes, have been reported in AD." (PMID 37958816, 2023). "Pre-pregnancy medication included dopamine agonists (15/43) and terguride (1/43) in addition to subsequent insulin therapy for gestational diabetes (N = 2) and type 1 diabetes mellitus (N = 1)." (PMID 37240522, 2023). "Insulin resistance, a major complication of diabetes, is a condition in which insulin-induced glucose uptake is impaired in insulin-sensitive tissues." (PMID 38066566, 2023). "Weight gain induced by intensive insulin therapy has long been recognized as a major problem in diabetes therapy, especially with NPH insulin." (PMID 37283948, 2023). "In vivo, using a rat model of diabetes, the supplementation increases lean body mass and insulin sensitivity and decreases blood glucose and serum glycosylated hemoglobin." (PMID 38004100, 2023).
diabetes (continued). "We conducted a meta-analysis to further evaluate and establish the associations between four common types of hypoglycemic agents [metformin, sulfonylureas, thiazolidinediones (TZDs), and insulin] and PC incidence in individuals with diabetes mellitus (DM)." (PMID 37497113, 2023). "Type 2 diabetes mellitus (T2DM) is caused by the combination of insulin resistance and insulin secretion deficiency from constant high plasma glucose." (PMID 37050065, 2023). "Individuals with DR are at a higher likelihood of needing medications to manage their diabetes, such as oral hypoglycemics or insulin." (PMID 38143687, 2023). "With an ever-increasing number of diabetes technologies that assist individuals living with insulin-requiring diabetes, large amounts of diabetes-related and user-entered behavioral data are generated." (PMID 36981436, 2023). "The ANSHIN study assessed the impact of non‐adjunctive CGM use in adults with diabetes using intensive insulin therapy (IIT)." (PMID 36864014, 2023). "Type 2 diabetes mellitus (T2DM) is characterized by impaired insulin secretion on a background of insulin resistance (IR)." (PMID 36984867, 2023). "Oral hypoglycemia medications can help patients with diabetes in its early stages, although most people eventually become insulin‐dependent." (PMID 37091967, 2023). "The recommendation to switch to the use of insulin in coronary artery patients with diabetes mellitus (a macroangiopathic complication) is now a classic piece of knowledge in cardiology books." (PMID 37745746, 2023). "In7, Random Forest (RF) algorithm was used for the early prediction of diabetes using a number of variables such as regular and ultralente insulin dose, socio-demographic factors, and hypoglycemic symptoms, to just name a few." (PMID 37225754, 2023). "Fucoxanthin, a carotenoid found in brown algae, has shown promise in diabetes management by stimulating glucose uptake in skeletal muscle cells and adipocytes, improving insulin sensitivity." (PMID 37763235, 2023). "Both decreased insulin sensitivity and impaired insulin secretion are common in Asian populations with diabetes, in contrast to Western populations." (PMID 34588362, 2023). "In the different types of diabetes mellitus (DM), some mechanisms lead to chronic hyperglycemia, ranging from an absolute deficit in insulin secretion (as in type 1 DM) to resistance to insulin (as occurs in DM type 2), among other mechanisms." (PMID 37359049, 2023). "Insulin has a fundamental metabolic effect in regulating blood lipids, which explains why patients with diabetes have dyslipidemia as a coexisting metabolic condition." (PMID 38049802, 2023). "Diabetes is characterized by high blood sugar levels resulting from issues with insulin secretion or function." (PMID 39698026, 2023). "For 35% of them (7/20), HG were transient and the remaining 20% (4/20) developed overt diabetes, currently treated with antidiabetic treatment (insulin and/or oral antidiabetics)." (PMID 36824650, 2023). "T1DM was diagnosed on the basis of acute onset of osmotic symptoms with or without ketoacidosis, severe hyperglycaemia [blood glucose > 13.9 mmol/l (>250 mg/dl)] and insulin requirement from the onset of diabetes." (PMID 37303388, 2023). "An insulin resistance and a reduced insulin production are at the foundation of this kind of diabetes." (PMID 36770873, 2023). "One example is insulin therapy of diabetics during pregnancy, where precise glucose homeostasis is vital to the well-being, both immediate and long-term, of mother and fetus." (PMID 37384782, 2023). "By accurately forecasting future glucose levels, these models can help individuals with diabetes better adapt their insulin, diet, and physical activity to acutely avoid hypoglycemia and chronically improve the time in range (70–180 mg/dL)." (PMID 37837098, 2023). "Diabetic mellitus (DM) is a metabolic disorder categorized by hyperglycemia due to inopportune insulin secretion." (PMID 36839915, 2023).
diabetes (continued). "Inflammation is considered an intrinsic feature of systemic diabetes/insulin resistance that involves the release of cytokines from adipose tissue which then impairs insulin action, affecting people with either type of diabetes." (PMID 36824442, 2023). "Animal studies on diabetes-induced rats revealed that CILN had a much higher oral bioavailability (15.6%) compared to free insulin (0.1%), demonstrating the potential of CS/alginate NPs as carriers for oral peptide drug delivery." (PMID 37765234, 2023). "The treatment of diabetes is mainly based on the administration of oral antidiabetics and the injection of insulin." (PMID 37396152, 2023). "Diabetes, a chronic metabolic disorder characterized by impaired insulin production or utilization, has reached epidemic proportions worldwide." (PMID 37763235, 2023). "We present thoughts around miRNA-mRNA networks and miRNAs as both therapeutic targets to improve insulin secretion and as circulating biomarkers of diabetes." (PMID 36869830, 2023). "This study is the first to demonstrate the ability of hemp root extracts to counteract STZ-induced diabetes in mice by preventing pancreatic islet dysfunction and insulin-signaling defects in muscle." (PMID 37175224, 2023). "C‐peptide levels and islet autoantibodies also represent potential biomarkers for the stratification of GLP‐1RA therapy in insulin‐treated diabetes." (PMID 37864379, 2023). "Type 2 diabetes mellitus (T2DM) is a severe chronic epidemic that results from the body’s improper usage of the hormone insulin." (PMID 37175908, 2023). "IF can enhance insulin sensitivity in the long-term and therefore needs to be practised by patients with diabetes." (PMID 37313231, 2023). "We found significant improvement in blood glucose, plasma insulin, and glucose tolerance, resulting in a reversal of diabetes in OPG-treated versus saline- or IgG-treated diabetic NOD mice." (PMID 37910614, 2023). "In diabetes, sustained high blood glucose levels can induce oxidative stress and inflammatory responses, thereby exacerbating insulin resistance and impacting pancreatic function, further deteriorating the condition." (PMID 38259272, 2023). "Participants (n = 32; 56% female participants) had a mean (SD) age of 46.1 (17.1) years, had HbA1c at 54.0 (6.8 mmol/mol) [7.1% (0.9%)], and had a diabetes duration of 27.5 (17.0) years; 56% were insulin pump users." (PMID 37334295, 2023). "Recent research proves that the possibility of diabetes is decided first by extrahepatic hostility towards insulin." (PMID 38094528, 2023). "Tau pathology is one of the main features of AD, and many studies have reported the impact of insulin dysfunction and diabetes on it." (PMID 37873836, 2023). "The isCGM should be proposed in each patient at the onset of diabetes when insulin therapy is required." (PMID 37676398, 2023). "This is typically due to a limited innate capacity to secrete insulin meaning even a small reduction in insulin secretion through aging or β‐cell exhaustion results in type 2 diabetes mellitus." (PMID 38011590, 2023). "Dry beans, commonly known as Phaseolus vulgaris, can lower the risk of diabetes and obesity due to their significant different activity on the blood sugar and insulin response, and therefore their potential utility for diabetes prevention and control." (PMID 37051367, 2023). "Zinc is also important in the treatment of diabetes as it is involved in the synthesis, storage, and secretion of insulin." (PMID 37791061, 2023). "The percentage of participants taking insulin for diabetes and suffering from other co-morbid conditions requiring prolonged treatment was 37% and 48 %, respectively." (PMID 37692709, 2023). "Both postprandial and pre-prandial blood glucose levels depend on gut absorption, meal content, gastric emptying, insulin secretion, etc.; long-standing uncontrolled diabetes can lead to gastroparesis." (PMID 38024160, 2023).
diabetes (continued). "Extensive research has been conducted on the management of diabetes using hypoglycemic medications, insulin, and dietary interventions." (PMID 38049802, 2023). "Drugs that target GLP-1 are mainly its receptor agonists; these drugs have replaced insulin as the main line of treatment for diabetes." (PMID 37686185, 2023). "The involvement of skeletal muscle in insulin resistance and reduced cellular responsiveness to insulin is significantly relevant to understanding the pathophysiology of metabolic disorders, particularly type 2 diabetes mellitus." (PMID 38137918, 2023). "Diabetes mellitus is a long-term metabolic condition characterized by insufficient insulin production, insulin action resistance, or both." (PMID 37822828, 2023). "Diabetes mellitus is a group of metabolic diseases that have a reduced effect or an impaired production of the hormone insulin as a common characteristic, which leads to elevated blood glucose levels." (PMID 38074488, 2023). "Insulin therapy has for many years remained the gold standard in controlling diabetes, but it has also proven effective in reducing urine albumin excretion and does not negatively hinder kidney function as it is cleared by the kidneys." (PMID 37090383, 2023). "Pre-COVID adherence in people taking oral diabetes medication in the UK was reported to range from 60% to 87%, with 71% adherence to insulin) compared with 74.6% for the two categories combined in this study." (PMID 36691578, 2023). "In recent years, it has been shown that circulating miRNAs can serve as means of communication among different insulin-sensitive tissues, mediating diabetes development and progression." (PMID 37958657, 2023). "Diabetes treatment involves complex algorithms and regimens, necessitating individualized treatment plans, especially when involved insulin." (PMID 37408067, 2023). "For GLP1-RA, markers of reduced insulin secretion, either directly measured (e.g. c-peptide or HOMA-B) or proxy measures such as diabetes duration, were associated with reduced glycaemic response to GLP1-RA in the majority of observational studies." (PMID 37131814, 2023). "Diabetes is a chronic endocrine, metabolic disease characterized by an insufficient or resistant insulin response." (PMID 37367922, 2023). "The American Board of Pediatrics recommends that all board-certified pediatricians be able to develop an insulin management plan for patients with diabetes." (PMID 36825276, 2023). "In this study, we investigated the effect of a pegylated, large 3D porous ferrisilicate/insulin nanoformulation for diabetes management." (PMID 36839915, 2023). "In obesity and diabetes, the liver becomes insulin resistant, leading to increased glucose production and release into the bloodstream." (PMID 37240215, 2023). "Type 2 diabetes (T2D) accounts for more than 90% of all diabetes cases, due to low insulin activity (insulin resistance) and slowed insulin production by pancreatic intestine cells." (PMID 38004427, 2023). "Further research is necessary to fully understand the intricate relationship between NOXs and insulin secretion and their potential therapeutic implications in diabetes." (PMID 38203517, 2023). "Increasing evidence suggests that IR is at the crossroads of metabolic syndromes (MetS) (e.g., obesity, diabetes mellitus, hypertension, and cardiovascular disease) in humans, affecting insulin-regulated pathways and many organs once IR is elevated." (PMID 37693717, 2023). "Treatment of diabetes has therefore focused on the management of blood glucose levels using oral hypoglycemic agents and insulin administration to hinder the onset and progression of microvascular complications." (PMID 36782199, 2023). "This work intends to be a proof of concept that coffee polysaccharides-derived microparticles can be used as drug delivery systems, opening new avenues for the future exploitation of pulmonary insulin administration for Diabetes Mellitus treatment." (PMID 37111698, 2023).